GM2A (ganglioside GM2 activator)
Diseases named in the same sentence as GM2A in open-access papers:
GM2A is named in the same sentence as 48 diseases in open-access papers, as found by Europe PMC text mining. Sharing a sentence is not in itself a finding about the gene and the disease. The quoted sentences say what the papers report.
GM2 gangliosidosis (23 papers, 2012 to 2026). A group of recessively inherited diseases characterized by the intralysosomal accumulation of G(M2) GANGLIOSIDE in the neuronal cells. "GM2 gangliosidosis is caused by a deficiency of one of the β-hexosaminidase lysosomal enzymes (Hex A, B, or S) or the GM2 activator protein (GM2A)." (PMID 39609393, 2024). "Although no actual information is available about the ganglioside GM2 activator (GM2A), it has previously been related to the AB variant of GM2 gangliosidosis." (PMID 36837912, 2023). "AB-variant GM2 gangliosidosis (ABGM2), the third type of GM2 gangliosidosis that was discovered by Konrad Sandhoff, is caused by mutation(s) in GM2A." (PMID 37298170, 2023). "The absence/defect of GM2A seems to be the cause of GM2 accumulation in neuronal tissues in patients with GM2 gangliosidosis." (PMID 36837912, 2023). "GM2 gangliosidosis, AB variant, is an extremely rare (only a few cases have been reported worldwide) autosomal recessive inherited disorder caused by mutations in the GM2A gene which encodes the GM2 ganglioside activator protein (GM2AP)." (PMID 29342918, 2018). "In presence of strong clinical presentation and normal lysosomal enzyme activity; GM2 gangliosidosis activator deficiency leading to AB variant was carried out by mutation analysis encompassing GM2 activator (GM2A) gene." (PMID 27402091, 2016). "GM2A is an established gene for GM2-gangliosidosis, AB variant (MIM: 272750)." (PMID 33456446, 2020). "A patient with clinical features of Omenn syndrome (OS) who did not harbor defects in genes known to be associated with OS, had a homozygous 691 kb deletion at 5q33.1 encompassing the GM2A gene associated with GM2-gangliosidosis, which was detected by chromosomal microarray." (PMID 30697212, 2018). "Notably, mice that are deficient in enzymes that we found to be downregulated in the Mwk cerebellum also display cerebellar dysfunction including Scp2 knockout mice, Smpd1-deficient mice, a model of Niemann-Pick disease, and Gm2a knockout mice, a model of GM2-gangliosidosis." (PMID 25908616, 2015). "GM2A, a lysosomal activator protein required for ganglioside GM2 degradation, is deficient or functionally compromised in the AB variant of GM2 gangliosidosis, which leads to neurodegeneration [Renaud and Brodsky, 2015, Conzelmann and Sandhoff, 1978]." (PMID 41394589, 2025). "GM2 activator deficiency, the rarest form of GM2 gangliosidosis, is caused by biallelic variants in GM2A encoding the GM2 activator protein required as a cofactor to β-hexosaminidase A in order to degrade GM2 ganglioside." (PMID 40297453, 2025). "AB-Variant GM2 gangliosidosis (ABGM2) is a rare and lethal genetic disorder caused by mutations in the GM2A gene that lead to fatal accumulation of GM2 gangliosides (GM2) in neurons of the central nervous system (CNS)." (PMID 38098938, 2023). "Destabilizing mutations in GM2A, which encodes the GM2A protein, lead to ABGM2, the rarest and likely most underreported form of GM2 gangliosidosis." (PMID 37834060, 2023). "GM2A is a lipid transport protein that binds to and stimulates ganglioside GM2 degradation, and mutations in this gene result in GM2 gangliosidosis, AB variant." (PMID 36131294, 2022). "GM2-gangliosidosis can be caused by mutations in three genes: HEXA (15th chromosome), HEXB (5th chromosome), and GM2A (5th chromosome)." (PMID 30524313, 2018). "Mutations in any one of these genes can result in one of three neurodegenerative diseases collectively known as GM2 gangliosidosis (HEXA, Tay-Sachs disease, MIM # 272800; HEXB, Sandhoff disease, MIM # 268800; and GM2A, AB-variant form, MIM # 272750)." (PMID 23483939, 2013). "Although biochemical data were suggestive of Sandhoff disease, other clinical forms of GM2 Gangliosidosis (Tay-Sachs and GM2-gangliosidosis, AB variant) were considered and HEXA and GM2A genes were analysed, excluding a potential clinical misdiagnosis." (PMID 22848519, 2012).
GM2 gangliosidosis (continued). "Three LSDs associated with GM2-gangliosidosis are Tay-Sachs disease (TSD, OMIM #272800), Sandhoff’s disease (SD, OMIM #268800), and GM2 activator protein deficiency (also called AB variant, OMIM #272750), and are associated with pathogenic variants in HEXA, HEXB, and GM2A, respectively." (PMID 35865957, 2022). "Mutations in any one of these three genes, HEXA, HEXB or GM2A, can cause the accumulation of the GM2 gangliosides and other terminal HexNAc-containing substrates, which make them relevant biomarkers of disease progression and treatment effects in GM2 gangliosidosis." (PMID 33259552, 2020). "Hence, deficiency of any of these proteins that are encoded by the HEXA, HEXB, and GM2A genes, respectively, causes excessive intra lysosomal accumulation of GM2 gangliosides and related glycolipids, especially in neuronal cells resulting in GM2 gangliosidosis." (PMID 32883051, 2020). "However, it is worth to point out that the clinical features presented by the patient are strongly suggestive of a GM2 gangliosidosis and the sequence analysis of the HEXA and GM2A genes, showing the absence of mutations enabled us to exclude other clinical forms of GM2 gangliosidosis." (PMID 22848519, 2012). "This suggests that GM2 accumulations in Gm2a−/− mice, although detectable and correctable, are insufficiently elevated to induce overt motor pathologies characteristic of the human form of ABGM2, or of other murine models of GM2 gangliosidosis." (PMID 37298170, 2023).
Tay-Sachs disease (13 papers, 2011 to 2025). GM2 gangliosidosis, variant B or Tay-Sachs disease is marked by accumulation of G2 gangliosides due to hexosaminidase A deficiency. "Then, we determined the levels of lyso-GM2 in plasma samples from patients with various types of GM2 gangliosidosis including Tay-Sachs disease, Sandhoff disease, and GM2A deficiency." (PMID 22205997, 2011). "Mutations in the genes encoding the α- (HEXA) and β-subunits (HEXB), or GM2A (GM2A) lead to Tay-Sachs Disease (TSD; OMIM #272800), Sandhoff Disease (SD; OMIM #268800) and AB-Variant GM2 gangliosidosis (ABGM2; OMIM #272750), respectively." (PMID 38098938, 2023). "The GM2 gangliosidoses are rare autosomal recessive genetic disorders that include Tay-Sachs disease (TSD, OMIM 272800), Sandhoff disease (SD, OMIM 268800) and GM2 ganglioside activator protein (GM2A) deficiency (variant AB, OMIM 272750)." (PMID 29342918, 2018). "Three clinically similar subtypes of GM2 exist: Tay-Sachs disease (TSD), Sandhoff disease (SD), and GM2 activator deficiency, which result from mutation of HEXA, HEXB, and GM2A genes, respectively." (PMID 34456684, 2021). "However, in lysosomal storage diseases (LSD) such as GM2 gangliosidosis, Tay-Sachs disease (TSD), and Sandhoff disease (SD), the cleavage of GalNAc is decreased or blocked due to mutations of HEX or an essential activator protein, GM2A." (PMID 40942141, 2025).
lysosomal storage disorders (5 papers, 2020 to 2022). "GM2-gangliosidoses are a group of three lysosomal storage disorders (LSDs) that result from a deficiency in one of the lysosomal enzymes β-hexosaminidases (Hex A, B, or S) or the GM2 activator protein (GM2A)." (PMID 35865957, 2022). "Notably, the accumulation of GM2A within lysosomes of neurons which occurs in Tay–Sachs disease, another lysosomal storage disorder, has led to neuronal death." (PMID 36453132, 2022). "The reason for elevated CSF GM2A in AD and LBD is currently unknown but likely reflects generalised lysosomal dysfunction, as elevated GM2A has been detected via urinary analysis in lysosomal storage disorders." (PMID 32804976, 2020). "Direct GM2A inhibitors have not been developed, but several cationic amphiphilic drugs, including desipramine and chloroquine, induce phospholipidosis and inhibit GM2 hydrolysis, suggesting that these drugs may be repurposed for GBM therapy." (PMID 35133980, 2022).
breast carcinoma (3 papers, 2020 to 2023). "The inferred subset GRN from the MCF7 breast cancer cell line highlights that the GM2A and PRKACA genes are activated and suppressed by several genes." (PMID 33168813, 2020).
epilepsy (3 papers, 2019 to 2025). A brain disorder characterized by episodes of abnormally increased neuronal discharge resulting in transient episodes of sensory or motor neurological dysfunction, or psychic dysfunction. "GM2A is associated with both antiepileptic and sedative medications, while ARSA is implicated in treatments for dystonia and epilepsy." (PMID 40008429, 2025). "Given the functional contributions of GM2A, HEXA, and HEXB to lysosomal degradation of GM2 gangliosides, we next investigated lysosomal localization of GM2 gangliosides in GSCs in comparison with nonmalignant neural cultures from epilepsy patient surgical specimens." (PMID 35133980, 2022).
Alzheimer disease (2 papers, 2020 to 2025). A progressive, neurodegenerative disease characterized by loss of function and death of nerve cells in several areas of the brain leading to loss of cognitive function such as memory and language. "In addition, many genes closely related to neurological diseases, such as Got1, ApoE, Gm2a, have been found to interact with TET1 in OPCs; and Cst3 is associated with dementia in Lewy body disease and Alzheimer's Disease." (PMID 32974003, 2020).
asthma (2 papers, 2020 to 2025). "Firstly, in MR analysis between proteins and pulmonary diseases, three proteins, including EFEMP1, GM2A, and NPNT, were identified that exhibit a causal relationship with COPD while five proteins were highlighted that have causal effect on asthma." (PMID 40136421, 2025). "They include RBM42, STX5, and TRIM41 in asthma, CYP27A1, GM2A, LGALS9, SPI1, and NLRC4 in COPD, as well as ATF3, PPP1R15A, ZFP36, SOCS3, NAMPT, and GADD45B in IPF." (PMID 31952466, 2020). "These genes included RBM42, STX5, and TRIM41 in asthma, CYP27A1, GM2A, LGALS9, SPI1, and NLRC4 in COPD, ATF3, PPP1R15A, ZFP36, SOCS3, NAMPT, and GADD45B in IPF, LRRC48 and CETN2 in asthma-COPD, COL15A1, GIMAP6, and JAM2 in asthma-IPF and LMO7, TSPAN13, LAMA3, and ANXA3 in COPD-IPF." (PMID 31952466, 2020).
gangliosidosis (2 papers, 2019 to 2020). A group of autosomal recessive lysosomal storage disorders marked by the accumulation of gangliosides. "The application of this NGS panel allowed us to identify a very rare form of GM2A-gangliosidosis and a NCL subtype in a single run." (PMID 32883051, 2020). "One of the novel pathogenic variants was identified in the GM2A gene, which is associated with an ultra-rare (or misdiagnosed) LSD, the AB variant of GM2 Gangliosidosis." (PMID 32883051, 2020).
Parkinson’s (2 papers, 2022). "For instance, GM2A, a lipid transfer protein, has reduced reduced concentrations in the CSF of Parkinson’s patients." (PMID 36482407, 2022).
psoriasis (2 papers, 2019 to 2023). An autoimmune condition characterized by red, well-delineated plaques with silvery scales that are usually on the extensor surfaces and scalp. "The network pharmacology results revealed that the key targets of active STT components, namely GM2A, REN, MMP12, RBP4, and S100A9, are primarily associated with psoriasis, potentially serving as the basis for the therapeutic effectiveness of STT." (PMID 37653756, 2023). "The network pharmacology results revealed that the primary targets of the active ingredients in STT were S100A9, GM2A, REN, MMP12, and RBP4, all of which were primarily associated with psoriasis." (PMID 37653756, 2023).
diabetic kidney disease (1 paper, 2020). Progressive kidney disorder caused by vascular damage to the glomerular capillaries, in patients with diabetes mellitus. "In a meta-analysis study of rat glomerular transcriptome profiling, it was confirmed that GM2A was highly expressed in various diabetic kidney disease rat." (PMID 32545899, 2020).
gastric cancer (1 paper, 2025). A primary or metastatic malignant neoplasm involving the stomach. "ROC analysis identified genes with high specificity and sensitivity for discriminating EBV+ gastric cancer, including GBP5, CMKLR1, GM2A and CXCL11 that play pivotal roles in immune response, inflammation, and cancer." (PMID 40110195, 2025).
glioma (1 paper, 2022). A benign or malignant brain and spinal cord tumor that arises from glial cells (astrocytes, oligodendrocytes, ependymal cells). "Based on published ADAR1 CLIP-Seq data generated in U87MG glioma cells, ADAR1 bound in the 3′-UTR of GM2A." (PMID 35133980, 2022).
lysosomal lipid storage disorder (1 paper, 2018). An inherited metabolic disorder in which harmful amounts of lipids accumulate in cells and tissues. "GM2 gangliosides are a group of lysosomal lipid storage disorders that resulted from disease-causing mutations in three autosomal recessive genes, including hexosaminidase A (HEXA), hexosaminidase subunit beta (HEXB) and GM2 ganglioside activator (GM2A)." (PMID 31428437, 2018).
malignant glioma (1 paper, 2019). A grade III or grade IV glioma arising from the central nervous system. "However, specific glycan heads in gangliosides such as GM2a, GM3, GM1b, Gb3, and Gb4 were significantly altered in malignant glioma cell lines." (PMID 31717732, 2019).
necrotizing enterocolitis (1 paper, 2015). Necrotizing enterocolitis (NEC) is a devastating disease that affects mostly the intestine of premature infants. "The aim of the present study was to investigate the association of neonatal necrotizing enterocolitis (NEC) with myeloid differentiation-(MD-2) and GM2 activator protein (GM2A) genetic polymorphisms." (PMID 25816011, 2015).
Obesity (1 paper, 2024). Accumulation of substantial excess body fat. "We observed significant upregulation of genes such as Cyp11a1, Fdx1, Flt1, Gm2a, and S100a6 in the G05 subpopulation under the influence of obesity." (PMID 38956667, 2024).
retinal diseases (1 paper, 2023). "We compared the significantly dysregulated genes identified in this screen (FDR <0.05) against genes linked to inherited retinal diseases and identified 5 genes: RGR, PRCD, CDH3, GM2A, and CYP2U1." (PMID 37115691, 2023).
silicosis (1 paper, 2022). Silicosis is a respiratory disease caused by breathing in (inhaling) silica dust. "For the first time, we found that cellular adhesion molecules (CAM), such as Gm2a, CHI3L1, LCN2, THBD, NADPH oxidase (NOXs) and vacuolar-ATPase are involved in pathogenesis of silicosis." (PMID 34991559, 2022).
Sphingolipidoses (1 paper, 2020). "Apart from the novel variants identified in the GLA gene, GM2A gene, and GALC genes, only one known GBA pathogenic variant was detected in Sphingolipidoses-related genes: the p.Leu483Pro in the GBA gene (patient P1)." (PMID 32883051, 2020).
infection (6 papers, 2015 to 2025). The state of being infected such as from the introduction of a foreign agent such as serum, vaccine, antigenic substance or organism. "In addition, the up-regulation of C1qb, C1qa, Lamp1, Lgals3, Gm2a, Gusb, Bax, and other genes helps to enhance the anti-tumor and anti-infection ability of the immune system." (PMID 40767963, 2025). "Lentivirus was employed to express untagged GM2A, and human neurons were transduced on Day 5 at increasing MOI (multiplicity of infection)." (PMID 36131294, 2022).
tumor (6 papers, 2022 to 2025). "In summary, ADAR1 is recurrently associated with tumor-promoting functions across multiple cancer types—via editing of oncogenes (AZIN1, GM2A), suppression of innate immune signaling (PKR/MDA5), and stabilization of key proteins (KYNU)." (PMID 40852728, 2025). "Similarly to GM2A depletion, loss of either HEXA or HEXB decreased GSC growth and abolished tumor sphere formation." (PMID 35133980, 2022). "As in vivo tumor formation is an essential feature of GSCs, we interrogated ADAR1 and GM2A dependencies in proof-of-principle tumor xenograft experiments." (PMID 35133980, 2022). "Consistent with a critical role of GM2A in GSC maintenance, mice with transplanted GSCs expressing shGM2A displayed longer survival and reduced tumor volume compared with those transduced with the control shRNA." (PMID 35133980, 2022). "Glycolipid catabolism involving proteins such as GM2A, NAGA, and SGSH is more active in patients with a low necrosis rate, which may be closely related to the energy metabolism needs of tumor cells." (PMID 40989695, 2025). "In contrast, ADAR1 acts as an oncogene, promoting tumor cell proliferation through RNA editing and non-catalytic functions such as CDK2 mRNA stabilization and GSC maintenance via GM2A." (PMID 40852728, 2025).
neurodegenerative disease (3 papers, 2013 to 2025). A disorder of the central nervous system characterized by gradual and progressive loss of neural tissue and neurologic function. "While deficiencies in GM2A cause fatal neurodegenerative disease, it was not previously appreciated that physiologically relevant elevations in levels of GM2A would directly affect the integrity of human neurons." (PMID 36131294, 2022).
nervous system disease (1 paper, 2020). "For instance, in OPC protein–protein interaction (PPI) network, proteins involved in Golgi vesicle transport (such as Vamp3, Golga7, Vti1b and Snx1), Cell redox homeostasis (such as Tnx2 and Gsr), nervous system disease (such as Got1, Gm2a, Apoe and Cst3) and other functions were identified." (PMID 32974003, 2020).
GM2A also shares sentences with these, for which no sentence is quoted: Sandhoff disease (8 papers); cancer (3); AB-Variant GM2 gangliosidosis (2); Candida infection (2); dementia (2); atherosclerosis (1); candidiasis (1); cholangitis (1); chronic periodontitis (1); cognitive decline (1); dentatorubral-pallidoluysian atrophy (1); Dystonia (1); endothelial dysfunction (1); genetic disorder (1); gingivitis (1); GM1 gangliosidosis (1); Heart Diseases (1); Lewy body disease (1); Lipid storage disease (1); lung carcinoma (1); major depressive disorder (1); Niemann-Pick disease (1); Omenn syndrome (1); pulmonary diseases (1).